IGLV2-18 (immunoglobulin lambda variable 2-18)
Description:
V region of the variable domain of immunoglobulin light chains that participates in the antigen recognition. Immunoglobulins, also known as antibodies, are membrane-bound or secreted glycoproteins produced by B lymphocytes. In the recognition phase of humoral immunity, the membrane-bound immunoglobulins serve as receptors which, upon binding of a specific antigen, trigger the clonal expansion and differentiation of B lymphocytes into immunoglobulins-secreting plasma cells. Secreted immunoglobulins mediate the effector phase of humoral immunity, which results in the elimination of bound antigens. The antigen binding site is formed by the variable domain of one heavy chain, together with that of its associated light chain. Thus, each immunoglobulin has two antigen binding sites with remarkable affinity for a particular antigen. The variable domains are assembled by a process called V-(D)-J rearrangement and can then be subjected to somatic hypermutations which, after exposure to antigen and selection, allow affinity maturation for a particular antigen.
Synonyms: IGLV218; V1-5
Gene: Immunoglobulin variable (V) gene on chromosome 22 (22,734,607 to 22,735,089, forward strand). Ensembl gene ENSG00000211664.
Subcellular location: Secreted; Cell membrane
Gene Ontology:
Biological process: immune response
Cellular component: extracellular region; immunoglobulin complex; plasma membrane
Homologues: Paralogues in human: IGLV2-14 (92% identical), IGLV2-8 (90% identical), IGLV2-11 (89% identical), IGLV2-23 (85% identical), IGLV2-33 (76% identical), IGLV1-40 (75% identical), IGLV1-50 (72% identical), IGLV1-44 (69% identical), IGLV1-47 (69% identical), IGLV1-51 (66% identical), IGLV6-57 (66% identical), IGLV1-36 (64% identical), and 81 more.